STEAP4 (STEAP4 metalloreductase)
Description:
Integral membrane protein that functions as a NADPH-dependent ferric-chelate reductase, using NADPH from one side of the membrane to reduce a Fe(3+) chelate that is bound on the other side of the membrane. Mediates sequential transmembrane electron transfer from NADPH to FAD and onto heme, and finally to the Fe(3+) chelate. Can also reduce Cu(2+) to Cu(1+) (By similarity). Plays a role in systemic metabolic homeostasis, integrating inflammatory and metabolic responses (By similarity). Associated with obesity and insulin-resistance. Involved in inflammatory arthritis, through the regulation of inflammatory cytokines. Inhibits anchorage-independent cell proliferation.
Synonyms: STAMP2; TNFAIP9; FLJ23153; TIARP; SchLAH
Tractability: Small molecule: a structure with a bound ligand is known. Antibody: UniProt places it where antibodies can reach, with high confidence; its Gene Ontology location is reachable by antibodies, with high confidence; UniProt predicts a signal peptide or a membrane-spanning region. PROTAC: ubiquitination databases record sites on it.
Gene: Protein-coding gene on chromosome 7 (88,270,892 to 88,307,010, reverse strand). Ensembl gene ENSG00000127954.
Subcellular location: Cell membrane; Golgi apparatus membrane; Early endosome membrane
Subcellular location (Human Protein Atlas): Nucleoplasm; Plasma membrane
Pathways (Reactome):
Transport of small molecules: Transferrin endocytosis and recycling
Gene Ontology:
Molecular function: electron transfer activity; FAD binding; ferric-chelate reductase (NADPH) activity; heme binding; cupric reductase (NADH) activity
Biological process: protein homotrimerization; copper ion import; fat cell differentiation
Cellular component: early endosome membrane; extracellular exosome; Golgi membrane; membrane; plasma membrane; endosome; endosome membrane
Genetic constraint (gnomAD): Loss-of-function variants: 35 observed, 41.92 expected, observed/expected ratio (o/e) 0.83, 90% interval 0.64 to 1.11. The upper end of that interval is the gene's LOEUF score, 1.11, which puts it in group 4 of 6, group 1 being the genes least tolerant of losing a copy. Missense variants: 452 observed, 534.13 expected, observed/expected ratio (o/e) 0.85, 90% interval 0.78 to 0.92. Synonymous variants: 178 observed, 191.99 expected, observed/expected ratio (o/e) 0.93, 90% interval 0.82 to 1.05.
Homologues: Orthologues: chimpanzee STEAP4 (99% identical), macaque STEAP4 (97% identical), dog STEAP4 (87% identical), pig STEAP4 (87% identical), rabbit STEAP4 (86% identical), guinea pig STEAP4 (85% identical), mouse Steap4 (82% identical), rat Steap4 (81% identical), tropical clawed frog steap4.2 (69% identical), tropical clawed frog steap4 (69% identical), zebrafish steap4 (60% identical). Paralogues in human: STEAP2 (46% identical), STEAP3 (45% identical), STEAP1 (26% identical), STEAP1B (21% identical).
Diseases named in the same sentence as STEAP4 in open-access papers:
STEAP4 is named in the same sentence as 80 diseases in open-access papers, as found by Europe PMC text mining. Sharing a sentence is not in itself a finding about the gene and the disease. The quoted sentences say what the papers report.
prostate carcinoma (21 papers, 2013 to 2025). A carcinoma that arises from epithelial cells of the prostate gland. "Our mechanistic studies revealed that STEAP4+ myoCAF represent a distinct subtype associated with ENZ resistance in prostate cancer and indicated that TFE3 plays a pivotal role in this resistance mechanism." (PMID 40917018, 2025). "HES6 knockdown influenced the expression of two cell migration-associated genes—metalloproteinase 7 (MMP7) and ITGB2 —as well as STEAP4, which was previously implicated in prostate cancer cellular proliferation." (PMID 25864518, 2015). "Overexpression of STEAP4 is thought to increase ROS, and this may increase gene mutation frequency and the progression of prostate cancer." (PMID 36620542, 2022). "Building upon previous studies in which CAFs were involved in prostate cancer tumorigenesis, our study identifies a subset of innately enzalutamide‐resistant STEAP4+ myoCAF that drive therapy evasion through TFE3‐mediated transcriptional reprogramming." (PMID 40917018, 2025). "Previous research has shown that STEAP4 is abundantly expressed in prostate cancer cells in the Golgi complex and plasma membrane, with aberrant expression predicting it plays an essential role in the development of prostate cancer." (PMID 39668818, 2024). "As a relatively new member of the STEAP family, STEAP4 was found to be increased in human prostate cancers compared with normal prostate tissues, and is up-regulated in human colon cancer cells, predicting poor prognosis of patients with colon cancers." (PMID 34778263, 2021). "The expression of STEAP4 is also upregulated in prostate cancer, and its oncogenic role in prostate cancer is proved by several studies." (PMID 32802887, 2020). "Furthermore, our findings suggest that PC secreted by STEAP4+ myoCAF promotes resistance and inhibits apoptosis of prostate cancer cells in response to enzalutamide treatment." (PMID 40917018, 2025). "STEAP4 may cause the generation of reactive oxygen species (ROS) through its oxidoreductase activity, leading to the expression of transcription factor ATF4, which promotes the growth and progression of prostate cancer, eventually leading to chemoresistance." (PMID 39668818, 2024). "In situ hybridization of human prostate cancer specimens showed that STEAP4 is expressed in epithelial prostate cells, and that its expression is significantly higher in prostate tumors compared with normal glands, suggesting that they may play a role in prostate cancer development and progression." (PMID 32290196, 2020). "In prostate cancer, STEAP1, STEAP2, and STEAP4 are overexpressed, while STEAP3 expression is downregulated." (PMID 36011027, 2022). "STEAP4, a relatively new STEAP, has been demonstrated to promote prostate cancer, based on its ability to increase cell growth and colony formation." (PMID 34778263, 2021).
Obesity (12 papers, 2013 to 2025). Accumulation of substantial excess body fat. "•The regulatory mechanism underlying the increased ubiquitination of STEAP4 in VAT during obesity remains to be elucidated." (PMID 41317904, 2025). "In humans, the gene has been linked to obesity, while in sheep, STEAP4 and other members of the same gene family (STEAP3) have been associated with excess fat accretion in tails." (PMID 34529728, 2021). "Accumulating evidence has indicated that STEAP4 is a novel anti-obesity gene that is regulated by multiple factors, including nutritional stress, hormones, pro-inflammatory factors, and adipokines." (PMID 35747386, 2022). "Therefore, our data support that the downregulation of STEAP4 promotes obesity and related metabolic disorders by impairing adipocyte mitochondrial function, which is highly consistent with previous reports." (PMID 41317904, 2025). "This study presents the combined proteomic and ubiquitylomic analysis of visceral adipose tissue in lean and obese mice, identifies ubiquitination-mediated STEAP4 downregulation in obesity, and links STEAP4 to adipocyte mitochondrial function, offering obesity therapeutic insights." (PMID 41317904, 2025). "However, the upstream mechanism by which obesity promotes STEAP4 ubiquitination modification in adipocytes requires further research." (PMID 41317904, 2025). "And another study showed that STEAP4 knockdown in adipocytes may impair mitochondrial function, thereby promoting obesity-related metabolism dysfunction." (PMID 41317904, 2025). "In this study, we conducted an integrated comparative analysis of proteome and ubiquitylome of lean or obese VAT, and revealed that STEAP4 in VAT may be involved in HFD-induced obesity through abnormal ubiquitination modification." (PMID 41317904, 2025). "Studies in mice and humans have suggested that alteration of STEAP4 expression may contribute to metabolic disorders like obesity, insulin resistance, and type 2 diabetes." (PMID 38671371, 2024). "Therefore, we hypothesize that during obesity, STEAP4 in adipocytes undergoes accelerated degradation due to enhanced ubiquitination modification, leading to a decrease in its protein level." (PMID 41317904, 2025). "Feeding can also induce STEAP4 expression, with such a physiologic response being lost in ob/ob mice or HFD-induced obesity mice." (PMID 35747386, 2022).
Insulin resistance (11 papers, 2013 to 2025). Increased resistance towards insulin, that is, diminished effectiveness of insulin in reducing blood glucose levels. "Existing studies have clearly shown that STEAP4 deficiency leads to adipose tissue dysfunction, enhanced inflammation, and impaired insulin signaling, while overexpression can improve insulin resistance." (PMID 41317904, 2025). "Furthermore, under HFD feeding condition, MDM2 overexpression induced eWAT dysfunction such as cellular senescence, apoptosis, and inflammation, through ubiquitin-mediated STEAP4 degradation, eventually, exacerbating hepatic steatosis and insulin resistance." (PMID 35747386, 2022). "Finally, STEAP4 restoration in eWAT of Mdm2-AKI mice on a HFD rescued MDM2-induced adipose dysfunction, insulin resistance, and hepatic steatosis." (PMID 35747386, 2022). "Furthermore, STEAP4 restoration in eWAT of Mdm2-AKI mice improved MDM2-induced metabolic disorder, including adipocyte dysfunction, insulin resistance, and hepatic steatosis." (PMID 35747386, 2022). "Moreover, a marked increase in STEAP4 was obtained (8.9 -old), which is of interest as STEAP4 protein is found to be reduced in the liver of individuals with NAFLD, and overexpression in mice ameliorates liver steatosis and insulin resistance." (PMID 40032158, 2025).
colon cancer (8 papers, 2020 to 2025). "Consistent with these molecular changes, STEAP4 deficiency suppressed colon tumor cell growth in vitro and xenograft tumor growth in vivo." (PMID 40205952, 2025). "The current research findings reveal that STEAP4 deficiency acts as a protective factor against colitis-associated colon cancer in mice, demonstrated by reduced xenograft tumor size and weight upon STEAP4 knockdown." (PMID 40205952, 2025). "Moreover, our study uncovered that STEAP4 overexpression in colon cancer cells is associated with elevated levels of ROS." (PMID 40205952, 2025). "Importantly, this IL-17-induced STEAP4-dependent cellular copper uptake is critical for colon tumor formation in a murine model of colitis-associated tumorigenesis and STEAP4 expression correlates with IL-17 level and XIAP activation in human colon cancer." (PMID 32060280, 2020). "To examine whether STEAP4-mediated copper uptake exerts a direct impact on caspase-3 activation, we examined the cellular response to 5-FU in the STEAP4-inducible colon cancer cell line and in STEAP4-deficient colon organoids." (PMID 32060280, 2020). "Our investigation into the role of STEAP4 in colon cancer has yielded significant findings, with broad implications for understanding and potentially treating this malignancy." (PMID 40205952, 2025). "In murine models of colon cancer, systemic ablation of Steap4 halted iron overload and disease pathogenesis in mice." (PMID 40002391, 2025). "Our primary discovery involves the observation that STEAP4, found to be upregulated in various cancer types, plays a crucial role in colon cancer." (PMID 40205952, 2025). "This dynamic regulation suggests a complex interplay between STEAP4 and oxidative stress responses, providing new insights into the molecular landscape of colon cancer." (PMID 40205952, 2025). "This decrease in STEAP4 expression in colon tumors contrasts with our previous findings, highlighting the complexity of the relationship between STEAP4 and NQO1 and the need for further investigation." (PMID 40205952, 2025). "Collectively, these findings suggest that reducing STEAP4 expression is effective in modulating ROS homeostasis, activating non-ferroptotic cell death signaling pathways and suppressing colon tumor cell growth both in vitro and in vivo." (PMID 40205952, 2025). "Inflammatory cytokines, which mobilize Cu, are linked to Six-Transmembrane Epithelial Antigen of the Prostate 4 (STEAP4) activation, enhancing Cu uptake and X-Linked Inhibitory Apoptosis Protein (XIAP) activation, thereby suppressing apoptosis in colon cancer." (PMID 39676876, 2024). "To this end, we engineered an inducible STEAP4 expression system into the human colon cancer cell line Ls174t, which robustly expressed Flag-tagged STEAP4 upon doxycycline treatment." (PMID 32060280, 2020). "We found that STEAP4 overexpression significantly increases biologically available copper in a colon cancer cell line, which correlates with enhanced metastatic potential." (PMID 32060280, 2020). "The study further found that the hypoxia/HIF–2 alpha/STEAP4/mitochondrial iron/mitochondrial ROS axis promoted colitis and colon cancer development." (PMID 32410986, 2020). "Conversely, copper chelation abolishes enhanced hepatic colonization by colon cancer cells that overexpress STEAP4." (PMID 32060280, 2020). "Moreover, NQO1 mRNA expression negatively correlated with STEAP4 mRNA expression in colon tumor tissues." (PMID 40205952, 2025). "Unraveling how STEAP4 mediates autophagy in colon cancer cells could provide valuable insights into its multifaceted role in cellular processes." (PMID 40205952, 2025). "In addition, there is a study which identified that STEAP4 links to inflammation and colon cancer as a critical regulator of mitochondrial dysfunction." (PMID 34163523, 2021). "Next, we sought to determine whether IL-17-induced STEAP4-mediated cellular copper uptake contributes to colon cancer progression in human." (PMID 32060280, 2020).
colon cancer (continued). "Intestinal-specific STEAP4 overexpression in mice is associated with increased mitochondrial iron accumulation, heightened oxidative stress-responsive protein NAD(P)H quinone dehydrogenase 1 (NQO1) and augmented susceptibility to colon tumors." (PMID 40205952, 2025).
atherosclerosis (6 papers, 2015 to 2025). A disease characterized by the build-up of fatty material and calcium deposition in the arterial wall resulting in partial or complete occlusion of the arterial lumen. "Six-transmembrane epithelial antigen of prostate 4 (Steap4)-knockout mice develop hyperglycaemia and inflammation whereas Steap4 overexpression attenuates atherosclerosis in diabetic mice." (PMID 25817898, 2015). "Additionally, because high glucose (HG) increases IL6 only in Steap4-deficient [but not wild-type (WT)] adipocytes 14 while overexpressing Steap4 suppresses atherosclerosis in diabetic mice 18, we hypothesize that Steap4 overexpression may attenuate HG or S100B-induced effects in mesangial cells." (PMID 25817898, 2015). "The six-transmembrane protein of the prostate 2 (Stamp2), also known as six-transmembrane epithelial antigen of prostate 4 (STEAP4), has emerged as a regulator of leukocyte-driven inflammation in metabolic syndrome atherosclerosis, and pulmonary vascular remodeling." (PMID 34691017, 2021).
breast carcinoma (6 papers, 2020 to 2024). "Research has shown that STEAP4 not only plays a role in the development and progression of breast cancers 62,63, but also participates in the regulation of inflammatory responses in CRC54." (PMID 39668818, 2024). "The increased expression of STEAP4 is also found in colorectal cancer, hepatocellular carcinoma, and breast cancer." (PMID 32802887, 2020). "In conclusion, through analyzing multiple databases, it is suggested that among STEAP family members, STEAP1, STEAP2, and STEAP4 have low levels in patients with breast cancer." (PMID 32802887, 2020). "STEAP1, STEAP2, and STEAP4 are predicted to be the potential prognostic biomarkers for breast cancer patients, providing novel therapeutic strategies for them." (PMID 32802887, 2020). "This study also found the downexpression of STEAP4 in breast cancer, and the expression of STEAP4 is related to the prognosis of breast cancer." (PMID 32802887, 2020). "The high expression of STEAP4 in breast cancer patients is often accompanied by a long survival period." (PMID 32802887, 2020). "Similar findings of overexpression of STEAP4 have been shown in breast cancer HER2+ (human epidermal growth factor receptor 2) cells, where L1 (0.025–0.05 mM) and the HER2+ inhibitor Lapatinib caused significant inhibition of STEAP4 and significant reduction in breast cancer cell growth." (PMID 36430469, 2022). "Moreover, STEAP1, STEAP2, and STEAP4 are related to the prognosis of breast cancer patients, providing an important theoretical basis and clinical guidance for the development of therapeutic targets and drugs for breast cancer patients." (PMID 32802887, 2020). "The results from ONCOMINE showed downregulation of STEAP1, STEAP2, and STEAP4 in breast cancers." (PMID 32802887, 2020). "While STEAP3 was unrelated to any improvement in overall breast cancer patient OS, other studies have found a relationship between downregulation of the related STEAP1, STEAP2, and STEAP4 proteins and improved outcomes." (PMID 37064114, 2023). "Survival analysis revealed that breast cancer patients with high levels of STEAP1, STEAP2, and STEAP4 had a good prognosis, while those with low expression had high overall mortality." (PMID 32802887, 2020). "Furthermore, knockdown of STEAP4 also suppressed cell proliferation and enhanced the pharmacological effect of lapatinib (HER2 inhibitor) in HER2-overexpressing breast cancer, confirming its potential oncogenic role in breast cancer." (PMID 36140186, 2022).
hepatocellular carcinoma (6 papers, 2019 to 2026). A malignant tumor that arises from hepatocytes. "Recently, exon 3-spliced variant STEAP4 (v-STEAP4) has been found to be highly expressed in porcine lung and in HepG2 cells derived from human liver carcinoma cells." (PMID 36140186, 2022). "On the other hand, a more recent study showed that STEAP4 was hypermethylated and downregulated in the hepatocellular carcinoma when compared to the non-tumor liver tissues." (PMID 34833128, 2021).
colitis (5 papers, 2020 to 2025). Inflammation of the colon. "Mitochondrial iron dysfunction via STEAP4 has also been implicated in increased oxidative stress in colon tissues and as a result promoting inflammatory tissue injury and colitis-associated colon cancer." (PMID 33842315, 2021). "In addition, STEAP4 was highly induced in the inflamed colon, and deletion of STEAP4 from colonic epithelial cells impaired copper accumulation and tumorigenesis in the colon in a murine model of colitis-associated tumorigenesis." (PMID 32060280, 2020). "Our earlier findings revealed dysregulation in mitochondrial iron balance, enhanced ROS production and increased susceptibility to mouse models of colitis and CRC when STEAP4 is overexpressed in intestinal epithelial cells." (PMID 40205952, 2025). "Previous studies have shown that STEAP4 is highly induced in colon epithelial cells in a mouse colitis model." (PMID 32060280, 2020).